FNDC3B (fibronectin type III domain containing 3B)
Diseases named in the same sentence as FNDC3B in open-access papers (continued):
Sharing a sentence is not in itself a finding about the gene and the disease.
glioma (continued). "Overall, LINC00355/miR-1225/FNDC3B network may become a candidate target for glioma therapy." (PMID 34603558, 2021). "Moreover, qPCR also confirmed that FNDC3B was upregulated in 121 glioma samples." (PMID 34603558, 2021). "Besides, the FNDC3B levels in glioma cells were notably depressed when the cells were transfected with miR-1225 mimics, while miR-1225 inhibitors remarkably promoted the FNDC3B levels in glioma cells, which indicated that miR-1225 expressions were negatively correlated with FNDC3B expressions." (PMID 34603558, 2021). "K-M plots indicated that patients with high FNDC3B expression had worse OS and DFS than those with low expression in gliomas." (PMID 36275754, 2022). "Hsa-miR-129-5p, a tumor suppressor, is down-regulated in gliomas and inhibits glioma proliferation, migration and development by targeting TGIF2, WNT5A, DNMT3A, HOXC10, FNDC3B." (PMID 35601497, 2022). "Due to the low mutation rate, FNDC3B may not be a hypermutation gene in the glioma cohort." (PMID 36275754, 2022). "Our findings revealed the tumor-promotive roles of LINC00355 in the progression of glioma, indicating that LINC00355 exhibited ceRNA functions via modulating miR-1225/FNDC3B axis." (PMID 34603558, 2021). "In our study, the FNDC3B high-expression group displayed higher values for immune, stromal, and ESTIMATE scores than the FNDC3B low-expression group, indicating that the high expression level of FNDC3B is positively related to immune infiltration in gliomas." (PMID 36275754, 2022). "In addition, we systematically elucidated the expression levels of the FNDC3B in different cancer cells by querying the CCLE database and found that FNDC3B was highly expressed in glioma cell lines." (PMID 36275754, 2022). "Among pan-glioma, LGG, and GBM in the TCGA datasets, patients with higher FNDC3B levels presented shorter OS and DFS compared to patients expressing low levels of FNDC3B." (PMID 36275754, 2022). "In the brain and CNS cancers dataset, there were seven studies on the upregulation of FNDC3B and no studies on its downregulation." (PMID 36275754, 2022). "Since we had demonstrated that LINC00355 sponged miR-1225, and miR-1225 targeted FNDC3B in glioma cells, we wondered whether LINC00355 could regulate FNDC3B." (PMID 34603558, 2021). "However, the overall expression profile of FNDC3B and its potential role in the development and distinct clinical significance of glioma has not been fully elucidated." (PMID 36275754, 2022). "Moreover, further studies identified that non-canonical RNA-binding proteins PTRF and FNDC3B suppressed glioma cell growth and found that they can be used as potential prognostic biomarkers for GBM." (PMID 32272554, 2020).
keratoconus (11 papers, 2017 to 2026). A degenerative, structural disorder of the eye, characterized by a cone-shaped protrusion of the cornea. "As we know, previous studies mainly focused on the association of FNDC3B with glaucoma and keratoconus." (PMID 34222226, 2021). "For example, FOXO1, RXRA and FNDC3B are the 3 genes that showed genome-wide significant association with keratoconus." (PMID 28676647, 2017). "Based on our findings, we speculate that the clinical phenotype of mutations in FNDC3B may be HM for some people, and it may also be keratoconus for other people, so whether it is an HM candidate disease-causing gene remains to be further evaluated." (PMID 34222226, 2021). "In this study, FNDC3B is another keratoconus associated gene." (PMID 28676647, 2017). "FNDC3B has been identified in GWAS of keratoconus and corneal traits, although its functional role in corneal biology remains incompletely characterized." (PMID 41595486, 2026). "Since FNDC3B rs4894538 was in strong linkage disequilibrium with rs4894535 (R2 = 0.991 in the discovery set), which is an established SNP associated with CCT and keratoconus, we only carried STON2 rs2371597 forward to the replication stage." (PMID 32737415, 2020). "Finally, we identified three genes, NOX4, FNDC3B, and ADAMTS17, present in regions of significant local covariance that also have known associations with both keratoconus and body height." (PMID 37561511, 2023). "We identified 8 SNPs in 6 genes/loci that were associated with keratoconus, i.e., FOXO1 rs2721051, FNDC3B rs4894535 and BANP-ZNF469 rs9938149 for the overall combined cohorts, and RXRA-COL5A1 rs1536482, IMMP2L rs757219 and rs214884, and COL4A4 rs2229813 and rs2228557 for Whites." (PMID 28676647, 2017). "In conclusion, we have prioritized 8 SNPs in 6 genes/loci as significant genetic markers for keratoconus in Whites, including FOXO1 rs2721051, RXRA-COL5A1 rs1536482, FNDC3B rs4894535, IMMP2L rs757219 and rs214884, and BANP-ZNF469 rs9938149, and COL4A4 rs2229813 and rs2228557." (PMID 28676647, 2017).
colorectal cancer (9 papers, 2019 to 2024). A primary or metastatic malignant neoplasm that affects the colon or rectum. "In comparison to normal tissues, FNDC1 and FNDC3B were highly expressed in colorectal cancer using the Oncomine database." (PMID 36626432, 2022). "Additionally, the circ-FNDC3B derived from the FNDC3B gene plays a crucial role in various tumors such as gastric cancer, esophageal cancer, and colorectal cancer, it promotes tumor epithelial-mesenchymal transition (EMT), invasion, and metastasis by regulating E-cadherin and CD44." (PMID 37819576, 2023). "In colorectal cancer (CRC), tumor growth, angiogenesis, and liver metastasis were suppressed by exosomal circ-fibronectin type III domain-containing 3B (FNDC3B) overexpression by acting via the miR-97-5p/TIMP3 pathway." (PMID 38392967, 2024). "Additionally, FNDC3B was found to facilitate cell proliferation and invasion via phosphoinositide 3-kinase (PI3K)/mTOR signaling and further promote colorectal cancer progression." (PMID 38137388, 2023). "We here aim to comprehensively analyze the mRNA expression of FNDC1, FNDC3A, FNDC3B, FNDC4, FNDC5, and GPR116 in nonaffected and affected mucosal samples of patients with IBD or colorectal cancer (CRC)." (PMID 31093274, 2019).
breast carcinoma (7 papers, 2015 to 2023). "It is known that FNDC3B is highly amplified in esophageal, lung, ovarian, and breast cancer and it has been associated with the activation of several cancer pathways including PI3-kinase/Akt, Rb1, and TGF-β signaling." (PMID 31093274, 2019). "P values (p = 2 × 10−15 for breast cancer and p = 0.00057 for ovarian cancer) indicated that FNDC3B expression also correlated negatively with patient survival in other cancers." (PMID 27385217, 2016). "Furthermore, decreased FNDC3Awas found to be related with a poor RFS or OS in all subtypes of patients apart from luminal B. It’s worth noting that high FNDC3B expression was probably tied to completely opposite survival outcomes in different breast cancer subtypes and survival analysis methods." (PMID 36626432, 2022). "To validate the results of the Oncopression database analysis of FNDC3B, we examined its expression in various cell lines of GBM, prostate cancer, and breast cancer." (PMID 38137388, 2023).
gastric cancer (7 papers, 2019 to 2024). A primary or metastatic malignant neoplasm involving the stomach. "Previous studies illustrated that FNDC3B abundance was correlated with the development and invasion in CCs, HNSCs and gastric cancers, and it also predicted a poor prognosis." (PMID 38253702, 2024). "A potential interaction between FNDC3B and survival outcomes has also been observed in ovarian and gastric cancer." (PMID 36626432, 2022).
prostate carcinoma (6 papers, 2013 to 2023). A carcinoma that arises from epithelial cells of the prostate gland. "Among them, FNDC3B was identified as the direct and functional target of miR-143 in liver and prostate cancer." (PMID 30352587, 2018). "It is needed to clarify the mechanism by which FAD104/FNDC3B regulates invasion and metastasis of liver and prostate cancer cells." (PMID 25671570, 2015). "It is our novel discovery that miR-143 was up-regulated during the differentiation of prostate CSCs and promoted prostate cancer metastasis by repressing FNDC3B expression." (PMID 23383988, 2013). "Taken together, these findings suggested that miR-143 might modulate prostate cancer metastasis by targeting FNDC3B." (PMID 23383988, 2013). "Furthermore, the expression of miR-143 and FNDC3B in human clinical prostate cancer specimens is still unclear." (PMID 23383988, 2013).
glaucoma (5 papers, 2018 to 2023). Increased pressure in the eyeball due to obstruction of the outflow of aqueous humor. "Association of rs2472493 (ABCA1) and rs7636836 (FNDC3B) polymorphisms with the risk of primary angle-closure glaucoma compared to control under different genetic models." (PMID 35719397, 2022). "These processes and pathways play a critical role in glaucoma pathophysiology and could be the plausible mechanism(s) by which rs7636836 in FNDC3B might influence the risk of POAG." (PMID 36980976, 2023). "Rs7636836 in FNDC3B encoding an extracellular matrix protein may contribute to the regulation of the TGFβ pathway which is strongly implicated in glaucoma pathogenesis." (PMID 36980976, 2023). "FNDC3B codes for an extracellular matrix protein that has a vital role in cell adhesion and growth signaling pathways, including TGFβ, and Wnt/β-catenin signaling all of which have been strongly implicated in glaucoma pathogenesis." (PMID 35719397, 2022). "However, none of the genes in these studies appear to relate CCT to the risk of developing glaucoma with the exception of FNDC3B." (PMID 29370175, 2018). "Polymorphisms rs2472493 near ABCA1, rs7636836 in FNDC3B, and rs61275591 near the ANKRD55–MAP3K1 genes were previously reported to exhibit genome-wide significance in primary open-angle glaucoma (POAG)." (PMID 36980976, 2023). "The expression of FNDC3B has been demonstrated in all the ocular tissues involved in glaucoma." (PMID 36980976, 2023). "Accordingly, we investigated the genetic association of two previously reported primary open-angle glaucoma (POAG)-related gene polymorphisms, rs2472493 (A > G) in ABCA1 and rs7636836 (C > T) in FNDC3B, in primary angle-closure glaucoma (PACG) and pseudoexfoliation glaucoma (PXG)." (PMID 35719397, 2022). "Minor allele frequency of rs2472493 in ABCA1 and rs7636836 in FNDC3B genes according to glaucoma types and gender." (PMID 35719397, 2022). "Given the overlapping clinical manifestations and common genetic variants reported among glaucoma types, we investigated the association of two POAG-related gene polymorphisms, rs2472493 in ABCA1 gene and rs7636836 near FNDC3B, in the PACG and PXG patient cohort of Saudi origin." (PMID 35719397, 2022). "Furthermore, FNDC3B is expressed in all the primary eye tissues relevant to glaucoma." (PMID 35719397, 2022). "ABCA1, FNDC3B, and ANKRD55–MAP3K1 are all highly expressed in the tissues relevant to glaucoma, supporting their plausible role in ocular development and glaucoma-related phenotypes." (PMID 36980976, 2023).
melanoma (5 papers, 2015 to 2026). A malignant, usually aggressive tumor composed of atypical, neoplastic melanocytes. "Moreover, it remains unknown whether miR-143 regulates metastasis of melanoma cells, and FAD104/FNDC3B expression." (PMID 25671570, 2015). "On the other hand, a previous study has shown that FNDC3B directly interacts with the signal transducer and activator of transcription 3 (STAT3) and inhibits its activity in melanoma cells." (PMID 41574767, 2026). "FNDC3B has been reported to suppress invasion and metastasis by inhibiting the phosphorylation of STAT3 in melanoma cells." (PMID 38137388, 2023). "On the contrary to melanoma cells, this study showed that increased STAT3 phosphorylation by FNDC3B silencing could play a role in suppressing cell migration, invasion, and stemness in GBM cells." (PMID 38137388, 2023).
acute myeloid leukemia (4 papers, 2022 to 2024). Acute myeloid leukemia (AML) is a group of neoplasms arising from precursor cells committed to the myeloid cell-line differentiation. "A high FNDC3B expression was correlated with a better prognosis of OS and DFS in skin cutaneous melanoma (SKCM) as well as OS in acute myeloid leukemia (LAML)." (PMID 36275754, 2022).
colon cancer (3 papers, 2022 to 2024). "In colon cancer cell lines and tissue, circ FNDC3B is mostly localized in the cytoplasm, and its over-expression inhibits the proliferation, invasion, and migration of colon cancer cells." (PMID 36338714, 2022). "Similarly, hsa_circ_0006156 from FNDC3B has been reported to inhibit Snail expression by encoding a 218aa protein, thus promoting the tumor inhibitory effect of FBP1 in colon cancer." (PMID 38802851, 2024). "Mechanistically, FNDC3B‐218aa exerted its tumour suppressive effect by acting on the Snail/FBP1/EMT axis, and FNDC3B‐218aa suppressed Snail expression, subsequently upregulating FBP1 and inhibiting EMT in colon cancer cells." (PMID 37070530, 2023).
myocardial infarction (3 papers, 2020 to 2022). Gross necrosis of the myocardium, as a result of interruption of the blood supply to the area, as in coronary thrombosis. "In a mouse model of myocardial infarction, circFndc3b, transcribed from its parent gene Fndc3b, was significantly downregulated in heart tissues 3 days post-myocardial infarction compared with the sham group." (PMID 32585625, 2020). "Furthermore, the overexpression of circ-Fndc3b regulated the function of endothelial cells, diminished apoptosis in CMs in vitro, augmented angiogenesis, restricted the size of the infarct, maintained cardiac function and integrity of post-myocardial infarction, and mediated cardiac repair." (PMID 36140705, 2022).
pancreatic cancer (3 papers, 2022 to 2024). "A necroptosis-relevant risk model was developed for predicting pancreatic cancer survival and responses to immuno- and chemotherapy, comprising MYEOV, HDAC4, TLDC1, PITPNA, FNDC3B, HMGXB4, and BAX." (PMID 35662734, 2022). "However, the precise role of FNDC3B in the progression of pancreatic cancer (PC) still remains to be elucidated." (PMID 38581008, 2024). "Out of 11 ITGA3, MET, FNDC3B, PPP1R14B and KIAA0513, including PLAU, were previously reported as individual prognostic markers in the pancreatic cancer TCGA-PAAD cohort." (PMID 36591282, 2022). "BAX, FNDC3B, HDAC4, HMGXB4, MYEOV, and TLDC1 displayed upregulated expressions in pancreatic cancer than normal tissues." (PMID 35662734, 2022).
tongue squamous cell carcinoma (3 papers, 2021 to 2022). A squamous cell carcinoma that arises from the tongue. "According to the data from TCGA, FNDC3B was upregulated in head and neck squamous cell carcinoma and was found to be an oncogene in tongue squamous cell carcinoma." (PMID 35060189, 2022).
acute promyelocytic leukemia (2 papers, 2020 to 2025). An aggressive form of acute myeloid leukemia (AML), characterized by arrest of leukocyte differentiation at the promyelocyte stage, due to a specific chromosomal translocation t(15;17) in myeloid cells. "Notably, it was found that the fusion gene FNDC3B::RARB was related to all-trans retinoic acid resistance in acute promyelocytic leukemia (APL), which indicated the potential role of RARB in leukemia treatment." (PMID 39723714, 2025). "In acute promyelocytic leukemia (APL), FNDC3B may promote pathogenesis by fusing to retinoic acid receptor α (RARA)." (PMID 32272554, 2020).
cervical squamous cell carcinoma (2 papers, 2021 to 2022). A squamous cell carcinoma arising from the cervical epithelium. "In cervical squamous cell cancer, FNDC3B inhibition hampers cancer cell proliferation and invasion." (PMID 34976823, 2021).
endometriosis (2 papers, 2014 to 2018). The growth of functional endometrial tissue in anatomic sites outside the uterine body. "An increased expression of miR-143 represses the transcription of FNDC3B, and thus, would promote cell invasion and migration in endometriosis." (PMID 29463003, 2018). "We suspected FNDC3B may also be the direct and functional target of miR-143 in endometriosis which had the similar clinicopathological features to malignant tumors, such as local invasion and distant metastasis." (PMID 25408705, 2014).
exfoliation syndrome (2 papers, 2019 to 2022). An autosomal dominant disorder caused by mutations in the LOXL1 gene, encoding lysyl oxidase homolog 1. "Genotype association analysis of rs7636836 variant in FNDC3B in pseudoexfoliation glaucoma." (PMID 35719397, 2022).
Hypertension (2 papers, 2022 to 2024). The presence of chronic increased pressure in the systemic arterial system. "ULK4 and FHIT genes have 17 and 10 EH-associated SNPs, respectively, while FNDC3B, FHIT, NPPC-DIS3L2, GLI2, and RBM47 include SNPs that have a ≥4 log-p value association with hypertension in the studied cohort." (PMID 35629146, 2022). "In addition, we identified 21 common genes that are shared between the GWAS and text mining analyses; of these, FNDC3B, FHIT, NPPC-DIS3L2, GLI2, and RBM47 genes are the most highly associated with hypertension." (PMID 35629146, 2022).
leukemia (2 papers, 2024 to 2025). A malignant (clonal) hematologic disorder, involving hematopoietic stem cells and characterized by the presence of primitive or atypical myeloid or lymphoid cells in the bone marrow and the blood. "Several of the top 20 APL super enhancers are linked to genes known to have functional roles in leukemia, for example RNF216, FSCN1, FNDC3B, HSP90B1, C12orf75, and JARID2, among them, JARID2 is a hematopoietic tumor suppressor through recruiting PRC2 to repress self-renewal pathways." (PMID 41168841, 2025). "Fusion genes involving FNDC3B have been identified in HCC and leukemia." (PMID 38403291, 2024).
liver cancer (2 papers, 2022 to 2023). An epithelial or non-epithelial malignant neoplasm that arises from the liver. "Additionally, compared to normal liver tissues, FNDC3A and FNDC4 showed lower expression, while FNDC3B and FNDC8 displayed higher expression in liver cancer." (PMID 36626432, 2022).
osteosarcoma (2 papers, 2023 to 2025). A usually aggressive malignant bone-forming mesenchymal neoplasm, predominantly affecting adolescents and young adults. "In this study, we identified a circFNDC3B/FNDC3B mRNA imbalance was involved in the malignant processes of osteosarcoma." (PMID 38129874, 2023). "The RBM47 and IGF2BP1 mediated circular FNDC3B/FNDC3B mRNA imbalance was involved in the malignant processes of osteosarcoma in vitro and in vivo." (PMID 38129874, 2023).
adrenal cancer (1 paper, 2023). A carcinoma involving a adrenal gland. "Among the 17 organs with a statistically significant difference, 16 exhibited an increase in FNDC3B expression in cancer tissues, the exception being adrenal cancer, which displayed a decrease." (PMID 38137388, 2023).
alcoholic liver diseases (1 paper, 2024). A disorder caused by damage to the liver parenchyma due to alcohol consumption. "For example, in both in vivo and in vitro models of alcoholic liver disease (ALD), the overexpression of miR-192-5p markedly reduced the expression of fibronectin type III domain-containing protein 3B (FNDC3B) in hepatocytes." (PMID 39717848, 2024).
Alzheimer’s dementia (1 paper, 2023). "To specifically verify the expression of FNDC3B in brain pathologies, we compared expression levels across 2510 samples, which included Alzheimer’s dementia, major depressive disorder (MDD), epilepsy, Parkinson’s disease, and brain tumors of varying grades and molecular specifications." (PMID 38137388, 2023).
bladder cancers (1 paper, 2023). "Out of 20 organs, a statistically significant difference in FNDC3B expression in cancer tissues was observed in 17 organs as compared to normal tissues, and no such difference was observed in the thyroid, ureter, and bladder cancers." (PMID 38137388, 2023).